IL22 (interleukin 22)
Diseases named in the same sentence as IL22 in open-access papers (continued):
Sharing a sentence is not in itself a finding about the gene and the disease.
influenza infection (continued). "IFNλR–/– mice were shown to produce increased levels of IL-22 following influenza, S. aureus super-infection." (PMID 32582219, 2020). "More recently, it was described that IL-22-mediated tight junction formation also plays a role in conferring protection against influenza infection and bacterial superinfection." (PMID 33003458, 2020). "IL-22R is upregulated in alveolar epithelial cells after influenza-induced injury, and IL-22 promotes recovery of those damaged cells." (PMID 32974217, 2020). "While IL-22 expression is increased over the course of influenza infection in mice, the amounts of IL-22BP concurrently decrease, augmenting cytokine activity in the resolution phase of infection." (PMID 32637365, 2020). "IL-22 has been established in the lung as a cytokine that is essential for repair following influenza infection." (PMID 31416461, 2019). "IL-22, also has critical functions in host defense and in maintaining epithelial integrity during influenza infection." (PMID 30761149, 2019). "In models of influenza infection, IL-22−/− mice exhibit increased morbidity and mortality correlative with decreased airway epithelial integrity and increased apoptosis of epithelial cells during the resolution of infection." (PMID 29988424, 2018). "Conventional NK cells were shown to be a major source of IL-22 during influenza infection and adoptive transfer of IL-22-competent conventional NK cells to IL-22−/− mice was shown to rescue epithelial cell regeneration." (PMID 29988424, 2018). "In respiratory infections, IL-22 provides critical immunity against Klebsiella pneumoniae, Streptococcus pneumoniae, Chlamydia muridarum, influenza, as well as the CF pathogen Aspergillus fumigatus." (PMID 27375092, 2016). "IL-22 is also important for the regeneration of tracheal and lung epithelial cells after influenza infection, preventing lung pathology and secondary bacterial infection." (PMID 27303405, 2016). "A similar anti-fibrotic role for IL-22 has been demonstrated following influenza infection with a corresponding benefit in preserving lung function." (PMID 27375092, 2016). "In these studies we demonstrated that preceding influenza infection resulted in decreased IL-1β and IL-23 expression and decreased subsequent IL-17 and IL-22 production." (PMID 25651926, 2015). "Replicating our previously published data there was attenuation of production of the Type 17 effector cytokines, IL-17A, IL-17 F, IL-22, and IL-23 in the influenza, S. aureus infected WT mice compared to WT mice that received S. aureus alone." (PMID 25651926, 2015). "The antimicrobial activity against several other intra- and extracellular pathogens in vivo is promoted by IL-22 and also the regenerative and inflammatory effect of this cytokine is documented during influenza infection." (PMID 23460846, 2013). "Further, the reduction in epithelial regeneration capability in influenza-infected IL-22 knockout mice could be restored by transferring ILC3 cells into the mice or treating it with recombinant IL-22." (PMID 39861052, 2025). "After influenza infection, IL-22 expression in the intestinal tract was significantly increased (p < 0.0001), and the expression level significantly decreased after feeding antimicrobial peptides (p = 0.0004), but did not recover to the level of the control group." (PMID 37571299, 2023). "However, in another study of pneumococcal superinfection following influenza infection in mice, treatment with exogenous IL-22 enhanced the lung barrier and reduced bacterial transmission but did not affect the bacterial burden." (PMID 37207185, 2023). "In preventing the progression of infections such as HIV and influenza, Th22/IL-22 exhibited protective anti-inflammatory characteristics, and their deleterious proinflammatory activities have been demonstrated to exacerbate other illnesses, including hepatitis B and Helicobacter pylori infection." (PMID 36839448, 2023).
influenza infection (continued). "However, there have been numerous studies on the effects of IL-22, a key cytokine of ILC3s, in influenza infections." (PMID 33968082, 2021). "IL22 has been shown by some to be necessary for epithelial repair following influenza infection." (PMID 34906172, 2021). "Interleukin 22 (IL22) is important in resolving lung injury following Flu infection." (PMID 34906172, 2021). "Since IL22 expression was suppressed following influenza infection in PM exposed mice, we determined whether treatment with rIL22 could protect against PM-exacerbated lung injury in influenza-infected mice." (PMID 34906172, 2021). "In addition, data suggest that IL22 is required to restrict the lung inflammation and bacterial secondary infection after influenza infection." (PMID 34906172, 2021). "Regulation of IL-22 signaling during influenza infection has also been studied." (PMID 32582219, 2020). "It is unclear whether IL-22 production by NK cells and T cells has a physiologically relevant protective role in human influenza infections." (PMID 32974217, 2020). "Delivery of IL-22 to mice decreased influenza mediated inflammation and lung leak." (PMID 32582219, 2020). "Finally, deletion of IL-22BP negative regulation of IL-22 was shown to decrease lung inflammation and injury compared with WT mice after influenza infection." (PMID 32582219, 2020). "IL-22 is generally studied for its protective effects during recovery from influenza infection." (PMID 32974217, 2020). "Initial study into the role of IL-22 during influenza infection produced limited results." (PMID 32582219, 2020). "IL-22–/– mice had decreased epithelial regeneration compared to WT mice after influenza infection." (PMID 32582219, 2020). "The mechanisms through which IL-22 prevents epithelial barrier dysfunction during influenza infection might include an inhibitory effect on the recruitment of inflammatory monocytes and a direct effect on the expression of genes involved in barrier functions." (PMID 30881357, 2019). "An important example of this is the role of IL-22 in influenza infection." (PMID 29988424, 2018). "IL-22−/− mice exhibit impaired regeneration of tracheal epithelium and exacerbated weight loss after clearance of influenza infection; a phenotype rescued by transfer of IL-22-proficient but not deficient NK cells." (PMID 27303405, 2016). "For example, administration of IL-22 may accelerate patient recovery from influenza or cytomegalovirus infections by improving lung barrier function or innate antiviral immune responses, respectively." (PMID 27303405, 2016). "Antibiotic treatment impairs the induction of protective immunity during influenza infection, suggesting that IL-22 modulation of the microbiota may impact on patient outcome." (PMID 27303405, 2016). "For example, pulmonary NK cells produce IL-22 in response to influenza infection." (PMID 27303405, 2016). "Importantly, co-infected IL-27Rα−/− mice have increased production of IL-17 F and IL-22 compared to co-infected WT mice, suggesting that IL-27 signaling significantly impacts Type 17 immunity during influenza, S. aureus co-infection." (PMID 25651926, 2015). "In addition, there was attenuation of gene expression of the Type 17 effector cytokines, IL-17, IL-22, and IL-23 in the influenza, S. aureus infected WT mice compared to WT mice that received S. aureus alone, similar to previously published data." (PMID 25651926, 2015). "Indeed, during HIV and influenza infections, IL-22 limits epithelial cell damage at mucosal surfaces." (PMID 24721575, 2014). "It is possible that TH17 pathway activation is elevated in severe influenza and that IL-17 may be detrimental while IL-22 is protective." (PMID 24324838, 2013). "In addition to benefits in influenza infection, it was recently demonstrated that IL-22 promotes immunity against respiratory syncytial virus; these benefits of IL-22 may also extend to SARS-CoV-2 infection." (PMID 33968082, 2021).
influenza infection (continued). "Thus, in the context of influenza infection, IL-22 appears to be protective." (PMID 32637365, 2020). "In mice, AhR has been shown to be indispensable for the development of IL-22+ NKp46+ innate lymphoid cells (ILCs) in the gut and the importance of IL-22 in protection against intestinal infections as well as lung tissue repair following severe influenza infection." (PMID 31134013, 2019). "We therefore measured the levels of several cytokines, including the pro-inflammatory TNF, IL-1β, IL-6, and IFN-γ, as well as IL-4, IL-10, IL-17A, and IL-22, in BAL samples from mice 5 days after influenza challenge." (PMID 40612502, 2025). "In addition, tissue barrier maintenance and repair by unconventional T cells may be important in protection against influenza; for example, iNKT cells stimulated by IL-1β and IL-23 produced IL-22, which protected the lung epithelium from influenza-mediated damage." (PMID 37536148, 2023). "Initial reports demonstrated only a minor role for IL22 during H1N1 influenza A virus infection in mice and as measured by influenza related morbidity and mortality." (PMID 34906172, 2021). "Thus, increased IL-9 and IL-22 levels may indicate increased cellular regulatory functions in the immune response and activation of the innate mechanisms of the immune system in response to influenza vaccines, in particular, containing immunoadjuvants." (PMID 32695114, 2020). "IL22 expression was significantly higher in PM-exposed mice at 0.5 and 1 dpe (without influenza infection) compared to vehicle-exposed mice." (PMID 34906172, 2021). "IL-22 and IFN-λ play major roles in influencing the outcome of bacterial infections of the lung, particularly by ESKAPE pathogens and important viral pathogens such as influenza and coronavirus." (PMID 32637365, 2020). "Antibody neutralization of IL-22 was not effective at reducing influenza mediated morbidity or mortality in mice, although a reductive effect on viral load was shown." (PMID 32582219, 2020). "While Th17 cells produce IL-22 in the lung in response to a variety of stimuli, their contribution in influenza infection is not as established as that of NK cells." (PMID 32974217, 2020). "In the lung, IL-22 is not found under naïve conditions but is produced by NKT cells during the initial innate response (48–72 h) to influenza infection." (PMID 31416461, 2019). "Although IL-22 does not affect viral loads during influenza, several independent groups have demonstrated the protective effect of IL-22 against epithelial damages caused by viral replication." (PMID 30881357, 2019). "IL-22 do not have significant effect on lethal influenza infection but is beneficial to sublethal infection." (PMID 28614380, 2017). "IL-22 has been shown to play a key role in controlling bacteremia in experimental gram-negative pneumonia and airway repair after influenza infection." (PMID 25254361, 2014). "In the lung, IL-22 plays a key role in controlling bacteremia in experimental gram-negative pneumonia and airway tissue repair after influenza infection." (PMID 25254361, 2014). "In vitro studies of influenza infection have revealed novel effector functions of iNKT cells including IL-22 production and modulation of myeloid-derived suppressor cells, but ex vivo characterization of human iNKT cells during influenza infection are lacking." (PMID 22916008, 2012). "Furthermore, in the lung tissue of mice with influenza, the novel fusion protein vunakizumab-IL22 (vmab-IL-22), a conjugate of IL-22 with anti-IL-17A antibodies, can inhibit IL-17A-mediated inflammatory responses and elevate the reparative capacity of IL-22." (PMID 36839448, 2023).
influenza infection (continued). "The role of IL22 in PM-exacerbated influenza severity has not been studied." (PMID 34906172, 2021). "Importantly, IL22 expression failed to increase following Flu infection in PM exposed mice." (PMID 34906172, 2021).
Arthritis (45 papers, 2013 to 2025). Inflammation of a joint. "IL-17 and IL-23, contribute to entheseal inflammation, arthritis and bone loss in PsA and together with IL-22 among other cytokines, play a role in keratinocyte proliferation in PsO." (PMID 37501212, 2023). "In this setting, we observed worsened arthritis manifestations, with increased clinical score and paw swelling in K/BxN serum‐triggered Il‐22‐deficient mice." (PMID 33734594, 2021). "The resulting arthritis exhibits reduced symptoms in Ahr‐deficient mice expressing lower IL‐22 levels." (PMID 33734594, 2021). "After IL-22-deficient rats were immunized with type II collagen, the incidence of arthritis and pannus decreased." (PMID 31828174, 2019). "Hypermethylation of the DMR within the first exon of arthritis-associated IL22 showed significant correlation (rho = 0.34, 95% CI 0.06–0.57, p = 0.01) between paired sperm and blood samples, independent of a CNV within the same region." (PMID 30779748, 2019). "The role of IL-22 in arthritis has been suggested in a collagen-induced arthritis model, in which IL-22-deficient mice exhibited decreased incidence of arthritis and less pannus formation." (PMID 30057583, 2018). "IL-22 also plays a dual role that is protective prior to the onset of arthritis and pathogenic after onset of arthritis." (PMID 28463993, 2017). "In summary, the present data provides evidence that joint IL-22 is pathogenic during the onset of antigen-induced arthritis in mice." (PMID 26330334, 2015). "In fact, experimental evidence presents contradictory effects (protective versus pathogenic) for IL-22 in the genesis of arthritis." (PMID 26330334, 2015). "This pathogenic effect of IL-22 is in keeping with reduced incidence of arthritis in IL-22 deficient mice." (PMID 24676270, 2014). "In this study we report that neutralization of IL-22 after onset of arthritis reduces severity of arthritis, implying a pathogenic role after onset of arthritis." (PMID 24676270, 2014). "To conclude, our data shows that reduced arthritis seen with anti-IL-22 antibody is associated with increased systemic Th1 responses and unaltered systemic Th17 responses." (PMID 24676270, 2014). "Our studies, so far, showed that neutralization of IL-22 in-vivo is associated with reduced severity of arthritis, increased frequency of Th1 cells and unaltered Th17 cells." (PMID 24676270, 2014). "Our studies show that neutralization of endogenous IL-22 after onset of arthritis is associated with reduction in the severity of arthritis supportive of a pathogenic role of IL-22 in the presence of inflammation." (PMID 24676270, 2014). "Previously, we have reported that administration of recombinant IL-22 prior to onset of arthritis is associated with reduction in the severity of arthritis, suggestive of a protective role prior to onset of arthritis." (PMID 24676270, 2014). "We show for the first time that IL-22 plays a dual role: protective prior to the onset of arthritis and pathogenic after onset of arthritis." (PMID 24676270, 2014). "In this report we show that administration of neutralizing antibody to IL-22 after onset of arthritis is associated with reduction in severity of arthritis, consistent with a pathogenic function of IL-22 during arthritis." (PMID 24676270, 2014). "Neutralization of IL-22 after onset of joint inflammation is associated with less severe joint inflammation." (PMID 24676270, 2014). "In this study we have administered neutralizing anti-IL-22 antibody prior to and after onset of arthritis to investigate the possible dual role and evaluate the mechanism underlying the pathogenic function of IL-22 during arthritis." (PMID 24676270, 2014). "So far our data showed that administration of anti-IL-22 after onset of arthritis is associated with reduced severity of arthritis and increase in IFN-γ responses." (PMID 24676270, 2014).
Arthritis (continued). "This view is supported by a previous report that IL-22−/− mice were less susceptible to collagen-induced arthritis than wild type mice." (PMID 24040208, 2013). "Conversely, we report worsened arthritis symptoms in Il‐22 deficient mice." (PMID 33734594, 2021). "Finally, we noted that serum IL‐6 levels were unmodified in Ahr‐ and Il‐22‐deficient mice following arthritis induction." (PMID 33734594, 2021). "Pro- and anti-inflammatory roles have been described for IL-22 in murine models of arthritis; for example, IL-22 was implicated in the enhancement or suppression of collagen-induced arthritis in mice co-treated with the parasitic nematode-derived molecule, ES-62." (PMID 27055194, 2016). "Moreover, in experimental models of arthritis, IL-22−/− mice were less susceptible to collagen-induced arthritis (CIA)." (PMID 26330334, 2015). "In summary our data shows, for the first time, that neutralization of endogenous IL-22 after onset of arthritis is associated with reduction in the severity of arthritis and administration of anti-IL-22 prior to onset of arthritis results in increased incidence and severity of arthritis." (PMID 24676270, 2014). "We also determined the concentrations of the cytokines IL-6, IL-10, IFNγ, TNFα, IL-17A, IL-17F, and IL-22 in serum samples of the arthritis patients." (PMID 40806470, 2025). "Consistent with the observed clinical and histopathological arthritis phenotype, we found increased expression levels of Tnf, Il1b and the IL-23 target genes Il17a and Il22 in the joints of IL-23 EEV injected mice." (PMID 33983951, 2021). "Nevertheless, in later stages of RA, IL-22 serum levels were observed to be negatively correlated with arthritis scores, and IL-22 administration locally decreased the inflammation level in the joints." (PMID 33407883, 2021). "Recent studies demonstrated that 1,25-dihydroxy vitamin D3 (1,25(OH) 2 VD3) and vitamin D3 receptor (VD-R) play a protective role in acute inflammation, but interleukin-22(IL-22) promotes inflammation, especially for arthritis." (PMID 34917427, 2021). "Here, we used the K/BxN serum transfer arthritis model (STA) to explore the impact of Ahr‐dependent Il‐22 expression on acute joint inflammation." (PMID 33734594, 2021). "Protection against serum‐induced arthritis in Ahr‐deficient mice likely reflects a reduced expression of major pro‐inflammatory cytokines and chemokines (such as CXCL1) masking the loss of IL‐22 anti‐inflammatory properties in the animals." (PMID 33734594, 2021). "Treatment with a neutralizing IL-22 antibody before onset of arthritis increases disease severity consistent with the previous study, whereas treatment after onset reduces disease severity." (PMID 33692792, 2021). "CCR6+ ILC3s from mice with arthritis expressed significantly higher levels of IL-17A and IL-22 mRNA than did comparable cells from control mice (p < 0.0001 and p = 0.015)." (PMID 31470891, 2019). "One administrated anti-IL-22 at early stage (score range of 0–4), and the other treated IL-22 prior to the onset of arthritis." (PMID 29182672, 2017). "Correspondingly, the IL-22-/- mice showed less susceptible to CIA than wild-type mice with lower clinical scores, reduced arthritis severity and lower degree of pannus formation." (PMID 29182672, 2017). "In the pathogenesis of arthritis in mice, IL-22 was reported to contribute to inflammation through inhibiting the expression of collagen and IgG30." (PMID 28526849, 2017). "Adiponectin injection resulted in an earlier onset of arthritis with bone erosion and high expression of IL-22 in CIA mice." (PMID 29182672, 2017). "Results in animal models are also debated, whereas IL-22−/− mice show reduced incidence of CIA, recombinant IL-22 administration prior to arthritis onset reduces disease severity, suggesting a dual role for IL-22 during RA development." (PMID 26284069, 2015).